FCGR2B (Fc gamma receptor IIb)
Diseases named in the same sentence as FCGR2B in open-access papers (continued):
Sharing a sentence is not in itself a finding about the gene and the disease.
infection (45 papers, 2013 to 2025). The state of being infected such as from the introduction of a foreign agent such as serum, vaccine, antigenic substance or organism. "They report an antibody Fc profile characterized by higher FcgR2b and reduced Fcgr3b for individuals who are more susceptible to breakthrough infections." (PMID 37322179, 2023). "GSEA at 24 h indicated that genes involved in infection, TLR, chemokine and cytokine signaling are enriched as before, but genes involved in phagocytosis are also enriched, including Vav1, Sirpa, Cdc42se1, Cdc42ep2, Fcgr2b/3, and Coro1a." (PMID 25888408, 2015).
bacterial infection (6 papers, 2015 to 2024). "The relative MoDC vs. Mo/MP signature encompasses additional genes that participate in “migration of cells” (p = 10−2.3, with S1PR3, CCL17, and SLC2A1), “bacterial infection” (p = 10−3.2, with CD1B, CD209, and FCGR2B), and “synthesis of nitric oxide” (10−2.5, with PLAU, IL1R2, and NOS2)." (PMID 26150816, 2015).
infectious disease (5 papers, 2013 to 2021). A disorder directly resulting from the presence and activity of a microbial, viral, or parasitic agent in humans. "Fc gamma receptor IIb (FcγRIIb) is an important inhibitory receptor that plays vital roles in regulating various immune response processes and the pathogenesis of many infectious diseases." (PMID 34879827, 2021). "As that was observed in infectious diseases, FCGR2B protective genotypes correlated lower gene expression and lower frequency of gross hematuria, latter of which was significantly associated mucosal infection and was an important indicator of episodes of IgAN." (PMID 23593433, 2013).
FCGR2B also shares sentences with these, for which no sentence is quoted: rheumatoid arthritis (25 papers); Insulin resistance (10); lymphoma (10); anaphylaxis (8); B cell lymphoma (8); inflammation (6); liver diseases (6); asthma (5); Cirrhosis (5); Kawasaki disease (5); kidney disease (5); multiple sclerosis (5); renal fibrosis (5); chronic inflammatory demyelinating polyneuropathy (4); chronic lymphocytic leukemia (4); diabetic kidney disease (4); Hypertension (4); leukemia (4); Osteopenia (4); acute kidney injury (3); cryptococcal infection (3); diffuse large B-cell lymphoma (3); endotoxemia (3); food allergy (3); influenza (3); lupus erythematosus (3); mantle cell lymphoma (3); non-alcoholic fatty liver disease (3); tuberculosis (3); type 2 diabetes mellitus (3).
A further 109 diseases each share a sentence with FCGR2B in 2 papers or fewer.